CALR (calreticulin)
Diseases named in the same sentence as CALR in open-access papers (continued):
Sharing a sentence is not in itself a finding about the gene and the disease.
cancer (continued). "CALR overexpression seemed to be an early stress event associated with TKIs treatment in vitro, and anti-CD47 treatment could increase phagocytosis of TKIs-exposed ALK+ cancer cells." (PMID 39767726, 2024). "Moreover, CALR was reported to regulate apoptosis process in cancers." (PMID 37735575, 2023). "In addition, various studies have demonstrated a correlation between calreticulin expression and overall patient survival, which clearly distinguishes calreticulin from other DAMPs suggesting potential use of calreticulin as a prognostic marker for success of the RT in various types of cancer." (PMID 36544712, 2022). "Hence we first analyzed the CALR expression in pan-cancer based TCGA and GETx database." (PMID 35264066, 2022). "Thus, therapeutic cancer vaccination against mutant CALR could be a new treatment modality in CALR-mutant MPN." (PMID 33718228, 2021). "Therefore, CALR can be identified as a key feature in eliciting an anti-cancer immune response." (PMID 34660305, 2021). "Apparently, calreticulin may be used as a target or a tool to oppose cancer stemness." (PMID 32268506, 2020). "Therefore, it is urgent to elucidate the potential role of CALR in antipancreatic cancer immunity." (PMID 32508042, 2020). "Furthermore, we found that the membrane proteins CDH2, EGFR, ITGA3, ITGA5, ITGB1, and CALR may have significant effect on cancer prognosis and outcomes, which were further validated in vitro." (PMID 33005184, 2020). "Thus, the relationship between CALR and cancer requires further investigation." (PMID 31632490, 2019). "Finally, such a prophylactic effect was lost when the cancer cells used for vaccination were depleted of CALR or HMGB1, as well as when exposure to 8-MOP plus 4J UVA irradiation was performed in the presence of an ATP-degrading enzyme or a monoclonal antibody blocking type I IFN receptors." (PMID 31371700, 2019). "Additionally, many cancer cells exhibit surface calreticulin expression, which may promote phagocytosis by macrophages." (PMID 27556507, 2016). "Ad[CE1A] significantly altered ICD markers (CALR, CD47 and ATP) in a beneficial dose and time dependent manner, aligning with Ad-driven effects observed in other cancers." (PMID 40247106, 2025). "Three (SPP1, CALR, and PRDX2) of the four enriched biomarkers in this study were found to be expressed mainly in cancer cells." (PMID 39939411, 2025). "Proteins discharged by cancer cells, such as HSP70, HSP90, and calreticulin, enhance the phagocytic action of DCs on stressed cancer cells." (PMID 39399642, 2024). "Calreticulin, which plays a broad role as a chaperone for many ER proteins including MHC I, was only positively correlated with IRF2 expression in some cancer types." (PMID 39281881, 2024). "On the other hand, adjuvanticity can be induced by cancer cells by the release of DAMPs, such as interferon (IFN), adenosine triphosphate and calreticulin along with related cytokines." (PMID 39091493, 2024). "In the process of ferroptotic cell death, cancer cells release DAMPs such as high-mobility group box 1 (HMGB1), calreticulin (CRT), and adenosine triphosphate (ATP) into the TME." (PMID 39335181, 2024). "(F) Favorable %survival with a high level of calreticulin and a low level of CD47 in all cancer patients." (PMID 36943734, 2023). "Out of all CSCs, about 42% were high in calreticulin, while only 9% were CC3-positive, which is line with our previous observations showing exclusive staining of cancer stem cells and dying cells." (PMID 36672243, 2023).
cancer (continued). "LRT treatment in vitro has been demonstrated to inhibit calcium influx and subsequently induce ER stress, resulting in the calreticulin upregulation and CD47 protein down-regulation in cancer cells." (PMID 37951973, 2023). "These viruses have demonstrated their capacity to trigger the release of critical DAMPs, such as ATP, HMGB1, calreticulin, HSP70, and HSP90 from dying cancer cells." (PMID 38077402, 2023). "For ICD prediction, DAMP molecules such as ATP, HMBG1 and calreticulin are usually detected, as they are known as the gold standard for predicting ICD in cancer cells." (PMID 37376425, 2023). "Among the DAMPs, the main actors are surface-exposed calreticulin (CRT), secreted adenosine triphosphate (ATP) and passively released HMGB1: they represent the main hallmarks of immunogenic cell death (ICD) of cancer cells." (PMID 36012593, 2022). "Here, we demonstrated in three cancer cell lines, including CT26.WT cells used for in vivo ‘abscopal’ experiments, that NBTXR3 + RT increased Ecto-CALR, compared to RT alone." (PMID 35659676, 2022). "DOX is known to activate and increase the early surface exposure of Calreticulin (CTR), an endoplasmic reticulum chaperone protein in cancer cells." (PMID 35214193, 2022). "The most common studied DAMPs were Calreticulin, HMGB1, ATP, and Heat Shock Proteins (HSP) 70 and 90, which were either expressed on the cancer cells or released." (PMID 36135095, 2022). "Adjuvanticity is modulated by DAMPs such as calreticulin and HMGB1 which act as adjuvants to boost the anti-cancer immune response." (PMID 35903697, 2022). "Docetaxel increases surface expression of the carcinoembryonic antigen (CEA), calreticulin (CRT), mucin-1 (MUC-1) and Fas in cancer cells." (PMID 35874714, 2022). "In clinical practice, radiotherapy and chemoradiotherapy were shown to induce the exposure of the ICD-related DAMPs calreticulin, HSP70 and HMGB1 when applied either as a pre- or post-operative protocol of different cancers." (PMID 36015189, 2022). "Processes associated with ICD result in the emission of DAMPs, such as HSP70, HSP90, calreticulin, HMGB1, ATP, type I IFN, cancer cell-derived nucleic acids, ANXA1, and others." (PMID 36015189, 2022). "For example, Calreticulin and SLAMF7, are pro-phagocytic receptors that are found in a variety of malignancies but are minimally expressed on healthy cells." (PMID 35865547, 2022). "Calreticulin expression was compared 48 h after photon RT, PrRT, and CIRT in four different human cancer cell lines." (PMID 33806808, 2021). "On the other hand, our results show that exposure of cancer cells to relatively high levels of CXCL12 induces the UPR and calreticulin release, which together with CD47 internalization contribute to cell phagocytosis by macrophages." (PMID 34561422, 2021). "DAMPs can be divided into three classes, exposed on the cell surface including calreticulin (CRT), released by cancer cells passively (such as HMGB1 and mitochondrial DAMPs), secreted by cancer cells actively (such as ATP)." (PMID 34094967, 2021). "Crucially, we detected some of the main biomarkers of ICD, namely, the translocation of calreticulin/ERp57, the release of HMGB1 and ATP, and the secretion of pro-inflammatory cytokines from the SeNps-treated dying cancer cells." (PMID 34771499, 2021). "Increased concentration of both calreticulin and HMGB1 have been observed in the blood of patients with various cancers." (PMID 33799560, 2021). "In fact, conventional anticancer drugs, such as anthracyclines, which have been shown to induce calreticulin and ERp57 translocation to the cell surface, induce ICD in cancer cells." (PMID 34771499, 2021).
cancer (continued). "In 2013, another gene implicated in the pathogenesis of MPN was revealed, namely the calreticulin gene (CALR), whose role in cancer was recognized previously." (PMID 33806036, 2021). "Following ICD-inducing intervention, the release of CALR, HMGB1, and ATP by dying cancer cells is observable within hours." (PMID 33281620, 2020). "The resulting heatmap showed that in the majority of malignancies, TILs were significantly correlated with multiple representative ICD mediators, such as CALR, LRP1, ANXA1, FPR1, TLR3, IFNAR1, PANX1, and P2RX7." (PMID 33299118, 2020). "Cytoplasmic release of calreticulin in bulk from the ER is prompted by massive cell stress or damage induced, for instance, by chemotherapy or UVC irradiation and exposed to cancer cell membranes (ecto-calreticulin)." (PMID 32872532, 2020). "In this regard, previous studies reported that certain cancer cells, including the NSCLC cell line A549, constitutively produce high levels of IL-8, thus induction of ecto-CALR exposure in this cell line would only seem plausible." (PMID 32560232, 2020). "Calreticulin (CALR), which is a calcium-binding chaperone and influences antigen presentation to cytotoxic T cells, is expressed in many cancer cells and promotes macrophages to engulf hazardous cancerous cells." (PMID 33194608, 2020). "Upregulation of the calreticulin gene is an adverse prognostic factor as the dominant pro-phagocytic signal in diverse tumors and is correlated with increased CD47 expression in cancer cells." (PMID 30079703, 2019). "ER chaperones such as calreticulin and certain heat-shock proteins, including HSP70, are exposed on the cancer cell surface, serving as DAMPs or “eat me” signals to be recognized by the immune system." (PMID 29864117, 2018). "These include (but are not limited to), CD47 up-regulation, inability to properly surface expose (ecto-) ‘eat me’ signals like calreticulin (CALR), or reduction in chemotactic signals facilitating sensing of cancer cells dying through ICD by the immune cells." (PMID 29707136, 2018). "A number of molecular chaperones are up-regulated in cancer in response to ER stress, including heat shock proteins (such as GPR78 and GPR94) and lectin-like chaperones (such as calnexin and calreticulin)." (PMID 30115016, 2018). "DAMPs also include “eat me” signals represented by exposure of calreticulin (CRT) and heat shock proteins (HSP) 70 and 90 on dying cancer cell membranes." (PMID 29849952, 2018). "Cancer cells undergoing ICD exhibit cellular release of ATP and exposure of certain ER chaperones on the cell surface, including calreticulin (CALR) and HSP70." (PMID 29864117, 2018). "Calreticulin (CRT), as a multifunctional protein, is involved in a spectrum of cellular processes including inflammation, autoimmunity, and cancer initiation/progression." (PMID 27672242, 2016). "Exposure to anthracylines was sufficient to induce translocation of calreticulin, HSP70 and HSP90 to the cell surface, and HMGB-1 release at later time point, but the clinical implications of ICD in these cancer types warrants further analysis." (PMID 25688334, 2015). "Of note, the balance between pro-phagocytic calreticulin and anti-phagocytic CD47 has also been described in multiple human cancer cells, with cancer cells often being characterized by CD47 overexpression to elude phagocytic removal." (PMID 25750898, 2015). "Some anticancer therapeutics efficiently kill cancer cells (hence promoting the release of HMGB1) and stimulate the secretion of both ATP and type I IFNs, but selectively fail to promote CALR exposure." (PMID 25964783, 2015). "After screening for proteins that are upregulated on the surface of cancer cells undergoing ICD, the endoplasmic reticulum (ER) protein calreticulin (CALR) exhibited increased translocation to the plasma membrane." (PMID 26486085, 2015).
cancer (continued). "This protein also functions as a molecular chaperone in the ER, like GRP94 and calreticulin, and GRP78 expression levels have been correlated with cisplatin resistance in certain cancers." (PMID 23755301, 2013). "In this pilot study, we evaluated the immunomodulatory effects of cowpea mosaic virus (CPMV) particles, which primarily activates innate immunity, and calreticulin nanoparticle (CRT-NP), which enhance immunostimulatory signals of immunogenic cell death in canine cancers." (PMID 40386779, 2025). "Calreticulin and these antigens activate antigen-presenting cells, including macrophages and dendritic cells, which release pro-inflammatory cytokines and activate CD8+ cytotoxic T cells to target cancer cells." (PMID 40061141, 2025). "This suggests that MCS selectively influences cancer cells expressing high levels of CALR without affecting the self-nonself recognition system mediated by SIRPα-CD47 and LRP-CALR interaction in macrophages." (PMID 39744689, 2025). "Since the phagocytosis of cancer cells by phagocytic cells involves the inhibitory SIRPα-CD47 interaction and the facilitatory LRP-cancer cell membrane CALR interaction, blockade of the LRP-CALR interaction impedes phagocytosis 46,47." (PMID 39744689, 2025). "Moreover, the hypomethylation activity of Aza increases the expression of calreticulin and CD47 on cancer cells, which increases both the pro-phagocytic and anti-phagocytic signals on the cells." (PMID 40361435, 2025). "Despite these changes, calreticulin knockdown did not affect the cancer cell response to CAR-Ms in either control or ATG9A KO OVCAR-8 cells, indicating these are likely secondary changes." (PMID 40595560, 2025). "RO-treated animals showed delayed malignant transformation, with no carcinomas at week 16 and increased expression of caspase-9, calreticulin, HMGB1, IFN-γ, and GM-CSF, indicating transient activation of antitumor immune responses." (PMID 40943044, 2025). "Even when cancer cells do not display CALR, studies have shown that macrophages themselves can secrete and/or display CALR to guide their phagocytosis." (PMID 38786045, 2024). "ICD plays an important role in cancer immunotherapy.[6b] To investigate the induction of ICD by DMPtNPS and RT treatment, the ICD biomarkers‐calreticulin (CRT), adenosine triphosphate (ATP), and high mobility group box 1 (HMGB1) were analyzed by immunofluorescence and FCM analysis, respectively." (PMID 38063844, 2024). "In this model, we have observed a transcriptional alteration of genes participating in processes that have a role in cancer and MPNs, revealing that these processes can be directly perturbed by mutant calreticulin without JAK2 or MPL intervention in the worm." (PMID 36611979, 2023). "We found that the combined treatment with radiation and ATR inhibitors can increase the release of HMGB1 and secretion of ATP, but not surface-presentation of CALR, in several human cancer cell lines." (PMID 37346039, 2023). "T lymphocytes promote calreticulin exposure, HMGB1 and IL-1β release, leading to DC uptake and cross presentation, providing a mechanism for amplification and self-perpetuation of the immune response against cancer neoantigens." (PMID 38077402, 2023). "More recent exploration of the cancer engulfment hypothesis has uncovered additional pathways including calreticulin, CD22, and CD24 that intersect with or run parallel to the SIRPα-CD47 pathway and are also potential targets in cancer." (PMID 36459066, 2023). "CALRmut specific T cells do not enrich in the bone marrow after therapeutic cancer peptide vaccination against mutant CALR." (PMID 37662956, 2023). "In addition to CALR, STING pathway also reflected a major factor behind cancer cells responsiveness toward BTZ." (PMID 36998701, 2023). "If cancer cells experience stress, injury, or death after PTT, they release DAMPs, such as heat shock proteins (Hsp), adenosine triphosphate (ATP), high-mobility group box 1 (HMGB1), and calreticulin (CRT)." (PMID 35454950, 2022).
cancer (continued). "Two of the most studied molecules are CALR and PDIA3, starting from their relation with cancer." (PMID 36213269, 2022). "In addition to the presence of DAMPs, exposure to irradiation can increase the expression of calreticulin (CRT) and phosphatidylserine (PS) on the surface of the cancer cells which also contributes to immune recognition of dying cells." (PMID 35529885, 2022). "Although calreticulin acts as a stimulatory signal to clear cancer cells, it apparently does not increase in SC and primary cultures of non-transformed human cells." (PMID 34638556, 2021). "Spontaneous or therapy-induced cancer cell death promotes the release in the TME of danger signals favoring ICD, a kind of cell death represented by ATP release, exposure of calreticulin on cancer cell surface and extracellular release of high mobility group box 1 (HMGB1)." (PMID 34680425, 2021). "The results of UALCAN database analysis showed that the mRNA expression levels of CALR, CREB3L3, FBOX6, and KDELR3 were increased in cancer tissues compared with normal tissues, while the mRNA expression levels of CRYAB, DNAJB4, and HSPB6 were decreased in BLCA." (PMID 34930465, 2021). "The Cancer Genome Atlas (TCGA) database of HNSCC patients was used to examine the expression of up-regulated genes, and CALR, HSPA5, and TRIB3 were found to be highly expressed relative to solid normal tissue in cancer and the survival rate was reduced in patients with high expression." (PMID 34580365, 2021). "Major DAMPs are ATP, calreticulin (CALR), high-mobility group box 1 (HMGB-1), type I interferon (IFN), annexin A1 (ANXA1), heat shock proteins 70 and 90 (HSP70, HSP90), or diverse nucleic acids, mainly cancer cell derived ones." (PMID 33947098, 2021). "Among them, BST2, CALR, DDIT3, HSPA5, and TRIB3 were significantly up-regulated in cancer tissues." (PMID 34580365, 2021). "Calreticulin can inhibit ER stress to inhibit EMT, which promotes cancer cells liver metastasis." (PMID 36046433, 2021). "Calreticulin (CALR), a crucial member of endoplasmic reticulum (ER) chaperones, was positively related to superior prognosis owing to the activation of anticancer immune in various cancers." (PMID 35027921, 2021). "We found that the localization of calreticulin on the cell surface significantly increased, suggesting that calreticulin exposure through FYN-mediated apoptosis may contribute to its anti-cancer properties." (PMID 34277435, 2021). "Many researches confirmed that CALR was related with cancer cell apoptosis, but miR-637 was not the only non-coding RNA to regulate CALR." (PMID 33209200, 2020). "In this study, we demonstrated that recombinant human milk peptide lactaptin (RL2) induces death of cancer cells with ICD hallmarks in vitro with the release of ATP and high-mobility group box 1 protein (HMGB1) and exposure of calreticulin and HSP70 on the external cell membrane." (PMID 32560527, 2020). "Furthermore, light-activated ZHER2:2395-IR700 triggered all hallmarks of immunogenic cell death, as defined by the translocation of calreticulin to the cell surface, and the secretion of ATP, HSP70/90 and HMGB1 from dying cancer cells into the medium." (PMID 33082328, 2020). "In addition, we observed that FOLFOX treatment increased surface expression of calreticulin (CRT) on tumor cells, a key determinant in immunogenic cell death-driven cancer immunity." (PMID 32391270, 2020). "Indeed, cancer cells succumbing to 8-MOP plus 4J UVA in vitro emitted key signals involved in the perception of RCD as immunogenic, including CALR exposure on the plasma membrane as well as ATP, HMGB1, and type I IFN release." (PMID 31371700, 2019). "Selective elimination of cancer cells is dependent on the presence of pro-phagocytic signals, like calreticulin, on cancer cells that are absent on normal cells." (PMID 32038992, 2019). "ICD cannot be achieved by cancer cell death that is not accompanied by calreticulin exposure, ATP and HMGB1 release." (PMID 28060726, 2017).